GNB5 (G protein subunit beta 5)
Description:
Enhances GTPase-activating protein (GAP) activity of regulator of G protein signaling (RGS) proteins, such as RGS7 and RGS9, hence involved in the termination of the signaling initiated by the G protein-coupled receptors (GPCRs) by accelerating the GTP hydrolysis on the G-alpha subunits, thereby promoting their inactivation. Increases RGS7 GTPase-activating protein (GAP) activity, thereby regulating mood and cognition (By similarity). Increases RGS9 GTPase-activating protein (GAP) activity, hence contributes to the deactivation of G protein signaling initiated by D(2) dopamine receptors. May play an important role in neuronal signaling, including in the parasympathetic, but not sympathetic, control of heart rate (By similarity).
Synonyms: GB5; HG2E; IDDCA; LADCI; LDMLS1; LDMLS2; gbeta5
Tractability: Small molecule: a structure with a bound ligand is known. Antibody: its Gene Ontology location is reachable by antibodies, with medium confidence. PROTAC: ubiquitination databases record sites on it; its protein half-life has been measured.
Gene: Protein-coding gene on chromosome 15 (52,115,100 to 52,191,392, reverse strand). Ensembl gene ENSG00000069966.
Subcellular location: Membrane
Subcellular location (Human Protein Atlas): Nuclear speckles; Centrosome; Rods & Rings
Pathways (Reactome):
Signal Transduction: Ca2+ pathway; Extra-nuclear estrogen signaling; G alpha (12/13) signalling events; G alpha (i) signalling events; G alpha (q) signalling events; G alpha (s) signalling events; G alpha (z) signalling events; G beta:gamma signalling through BTK; G beta:gamma signalling through CDC42; G beta:gamma signalling through PI3Kgamma; G beta:gamma signalling through PLC beta; G-protein activation; GPER1 signaling; Glucagon-type ligand receptors
Hemostasis: ADP signalling through P2Y purinoceptor 1; ADP signalling through P2Y purinoceptor 12; Prostacyclin signalling through prostacyclin receptor; Thrombin signalling through proteinase activated receptors (PARs); Thromboxane signalling through TP receptor
Neuronal System: Activation of G protein gated Potassium channels; Inhibition of voltage gated Ca2+ channels via Gbeta/gamma subunits; Presynaptic function of Kainate receptors
Metabolism: Adrenaline,noradrenaline inhibits insulin secretion; Glucagon-like Peptide-1 (GLP1) regulates insulin secretion
Cellular responses to stimuli: High laminar flow shear stress activates signaling by PIEZO1 and PECAM1:CDH5:KDR in endothelial cells
Disease: ADORA2B mediated anti-inflammatory cytokines production
Metabolism of proteins: Cooperation of PDCL (PhLP1) and TRiC/CCT in G-protein beta folding
Sensory Perception: Inactivation, recovery and regulation of the phototransduction cascade
Transport of small molecules: Vasopressin regulates renal water homeostasis via Aquaporins
Gene Ontology:
Molecular function: G-protein gamma-subunit binding; GTPase activator activity; protein binding; protein-folding chaperone binding; GTPase activity; signaling receptor complex adaptor activity
Biological process: G protein-coupled dopamine receptor signaling pathway; G protein-coupled receptor signaling pathway; signal transduction
Cellular component: cytosol; GTPase activator complex; membrane; cell tip; dendrite; nucleus; parallel fiber to Purkinje cell synapse; plasma membrane; postsynaptic membrane; presynapse; presynaptic membrane; synapse
Genetic constraint (gnomAD): Loss-of-function variants: 18 observed, 23.1 expected, observed/expected ratio (o/e) 0.78, 90% interval 0.54 to 1.15. The upper end of that interval is the gene's LOEUF score, 1.15, which puts it in group 5 of 6, group 1 being the genes least tolerant of losing a copy. Missense variants: 287 observed, 298.22 expected, observed/expected ratio (o/e) 0.96, 90% interval 0.87 to 1.06. Synonymous variants: 150 observed, 130.21 expected, observed/expected ratio (o/e) 1.15, 90% interval 1.01 to 1.32.
Homologues: Orthologues: chimpanzee GNB5 (99% identical), mouse Gnb5 (99% identical), pig GNB5 (99% identical), macaque GNB5 (99% identical), rat Gnb5 (99% identical), guinea pig GNB5 (97% identical), rabbit GNB5 (93% identical), tropical clawed frog gnb5 (92% identical), dog GNB5 (90% identical), zebrafish gnb5b (85% identical), zebrafish gnb5a (81% identical), Drosophila melanogaster Gbeta5 (60% identical), and 1 more. Paralogues in human: GNB1 (46% identical), GNB4 (46% identical), GNB3 (45% identical), GNB2 (45% identical).
Diseases named in the same sentence as GNB5 in open-access papers:
GNB5 is named in the same sentence as 63 diseases in open-access papers, as found by Europe PMC text mining. Sharing a sentence is not in itself a finding about the gene and the disease. The quoted sentences say what the papers report.
cardiac arrhythmia (8 papers, 2018 to 2025). Any disturbances of the normal rhythmic beating of the heart or MYOCARDIAL CONTRACTION. "Homozygous or compound heterozygous variants with at least one null allele in GNB5 cause intellectual developmental disorder with cardiac arrhythmia (IDDCA; MIM: 617173) associated with severe intellectual disability (ID)." (PMID 34573334, 2021). "MIM database indicates that mutations in GNB5 are associated with autosomal recessive disorders: infantile developmental disorder with cardiac arrhythmias (IDDCA, MIM# 617173) and language delay and ADHD/cognitive impairment with or without cardiac arrhythmia (LADCI, MIM# 617182)." (PMID 32477400, 2020). "Cardiac arrhythmia with bradycardia and ectopic beats represents a core symptom in GNB5 knock-out mouse models." (PMID 40565581, 2025). "Biallelic missense variants in GNB5 cause language delay and attention deficit-hyperactivity disorder/cognitive impairment with or without cardiac arrhythmia (LADCI; MIM: 617182), associated with mild or no ID." (PMID 34573334, 2021). "Pathogenic variants of GNB5 encoding the β5 subunit of the guanine nucleotide-binding protein cause IDDCA syndrome, an autosomal recessive neurodevelopmental disorder associated with cognitive disability and cardiac arrhythmia, particularly severe bradycardia." (PMID 33172956, 2021). "As cardiac arrhythmia in the form of bradycardia and ectopic beats is one of the core symptoms in IDDCA, we examined HRVs in Gnb5 mouse models with in vivo ECG monitoring." (PMID 33172956, 2021). "These sinus arrhythmias and conduction problems, reminiscent of arrhythmias observed in IDDCA subjects, further corroborate the involvement of Gnb5 gene in altered cardiac function and irregular heartbeat." (PMID 33172956, 2021). "In human populations, mutations in GNB5 have been reported to cause several diseases affecting intelligence, including language delay, ADHD/cognitive impairment with or without cardiac arrhythmia, and intellectual developmental disorder with cardiac arrhythmia." (PMID 32337102, 2020). "Homozygous or compound heterozygous variants in the GNB5 gene have been associated with either IDDCA (Intellectual Developmental Delay with Cardiac Arrhythmia, MIM#617173) or LADCI (Language delay and ADHD/Cognitive Impairment with or without cardiac arrhythmia, MIM#617182) human syndromes." (PMID 31817184, 2019).
Cognitive impairment (6 papers, 2018 to 2025). Abnormal cognition is characterized by deficits in thinking, reasoning, or remembering. "Furthermore, the residue S81L mutations in Gnb5 gene have been linked to neuropsychiatric disorder and cognitive deficits, though how this mutation influences these outcomes is still largely unclear." (PMID 40587559, 2025). "Given the observed downregulation of Gnb5 in AD and its negative correlation with Braak stages, along with evidence that Gnb5 deficiency in excitatory neurons causes memory deficits, we sought to evaluate whether overexpressing Gnb5 could mitigate cognitive deficits in 5xFAD mice." (PMID 40587559, 2025). "Supporting this notion, neuron-specific deletion of Gnb5 exacerbates Aβ plaque accumulation and leads to severe cognitive impairments, while hippocampal overexpression of Gnb5 reverses these effects." (PMID 40587559, 2025). "In contrast, excitatory neuron-specific knockout of Gnb5 results in severe cognitive deficits and increased Aβ plaque accumulation in 5xFAD mice." (PMID 40587559, 2025). "Collectively, these findings indicate that Gnb5 overexpression effectively alleviates cognitive deficits in 5xFAD mice." (PMID 40587559, 2025). "In this study, we demonstrate that Gnb5 regulates Aβ deposition and cognitive deficits by modulating BACE1 in AD." (PMID 40587559, 2025). "Together, these results suggest that Gnb5-CCKO mice exhibit cognitive impairment." (PMID 40587559, 2025). "Conditional knockout of Gnb5 in excitatory neurons resulted in cognitive impairments, whereas adeno-associated virus (AAV)-mediated overexpression of Gnb5 in the hippocampus ameliorated cognitive deficits and reduced Aβ deposition in 5xFAD mice." (PMID 40587559, 2025).
Alzheimer disease (5 papers, 2020 to 2025). A progressive, neurodegenerative disease characterized by loss of function and death of nerve cells in several areas of the brain leading to loss of cognitive function such as memory and language. "To further characterize the association of Gnb5 with late-onset Alzheimer’s disease (LOAD), we analyzed a large dataset (GSE44772) containing extensive clinical data from AD patients." (PMID 40587559, 2025). "Recently, the variants of Gnb5 are reported to be associated with the onsets of Alzheimer disease, suggesting the potential roles of Gnb5 in AD." (PMID 40587559, 2025). "According to one report, GNB5 can be AD-associated (Alzheimer disease) gene." (PMID 35342758, 2022). "Furthermore, a study of the expression of genes associated with Alzheimer’s disease in the presence of VD deficiency found that GNB5 expression was significantly reduced." (PMID 34684344, 2021). "These loci were enriched in genes with functions related to Alzheimer's disease and cognitive decline, including GNB5, GNG7 and PKN3 (p < 0.05)." (PMID 32525932, 2020). "In summary, our study demonstrates the significant impact of Gnb5 on cognitive function and Aβ plaque deposition, elucidating the mechanisms by which it regulates BACE1, which is central to Alzheimer’s disease progression." (PMID 40587559, 2025). "Given that G protein-coupled receptors (GPCRs) mediate the cellular response to most hormones/neurotransmitters, it is unsurprising that GPCR-related genes converge on normal aging (GNA15) and Alzheimer’s disease (GNAS, GNB5)." (PMID 34002691, 2021).
attention deficit-hyperactivity disorder (4 papers, 2016 to 2025). A disorder characterized by a marked pattern of inattention and/or hyperactivity-impulsivity that is inconsistent with developmental level and clearly interferes with functioning in at least two settings (e.g. at home and at school). "In addition, previous studies have indicated that GNB5 gene mutations can lead to severe speech disorders, motor delays, and attention deficit hyperactivity disorder (ADHD) as the main manifestations of recessive neurodevelopmental disorders." (PMID 34684344, 2021).
Bradycardia (4 papers, 2019 to 2023). A slower than normal heart rate (in adults, slower than 60 beats per minute). "For example, infusion of acetylcholine is known to cause sinus bradycardia, and variations in genes such as GNB5 can cause bradycardia by affecting the cholinergic responses." (PMID 36579854, 2023). "Human homozygote carriers of GNB5 pathogenic variants show severe bradycardia at rest with a maximal HR unchanged during exercise." (PMID 33172956, 2021). "The mechanism by which inherited genetic variation in GNB5 causes bradycardia has remained unexplored." (PMID 31208990, 2019). "ECG measurements showed that, conversely to IDDCA affected individuals who present with severe bradycardia at rest, Gnb5−/− mice have higher HRs in basal condition, especially during the day, the mouse sleeping phase." (PMID 33172956, 2021). "She later developed bradycardia and cardiac arrest, and upon re-phenotyping showed cone photo-transduction recovery deficit, all known only to GNB5-related disorders." (PMID 34573334, 2021). "In patients carrying pathogenic variants in GNB5, the maximal HR during exercise is unaffected, whereas severe bradycardia occurs at rest, indicating a relation between the mutant GNB5 and parasympathetic state." (PMID 31208990, 2019).
epilepsy (4 papers, 2022 to 2025). A brain disorder characterized by episodes of abnormally increased neuronal discharge resulting in transient episodes of sensory or motor neurological dysfunction, or psychic dysfunction. "The presentation of developmental delay in the first months of life in patients with GNB5-related neurodevelopmental disorder is associated with an unfavorable prognosis, characterized by severe or profound ID and, in some cases, epilepsy." (PMID 40565581, 2025). "Loss function of Gnb5 has been linked to neurological disorders such as epilepsy, retinal diseases, developmental disabilities, and hyperactivity." (PMID 40587559, 2025). "Homozygous and compound heterozygous GNB5 mutations result in a multisystem syndrome with cardiac conduction, and ocular and neurological disorders, including epilepsy." (PMID 38166692, 2024). "The S81L point mutation in Gnb5 has been previously linked to a spectrum of neurodevelopmental disorders, including language developmental disorders, ADHD, and motor delays and epilepsy." (PMID 40587559, 2025). "The first group is the studies that described the generation of patient-specific iPSC lines that carry genetic variants in genes associated with epilepsy, such as SCN1A, GNB5, LGI1, GRIN2A, KCNC1, or KCNA2." (PMID 36552721, 2022).
Intellectual disability (4 papers, 2018 to 2025). "The proband presented with early-onset intellectual disability, the severity of which was more in keeping with GNB5-related disorder than 3-MCC deficiency." (PMID 34573334, 2021). "Gnb5 is specifically expressed in brain and mutations in the Gnb5 gene cause a multisystem syndrome with intellectual disability in patients." (PMID 30864948, 2019).
colitis (2 papers, 2023). Inflammation of the colon. "Additionally, allocryptopine improved the intestinal barrier and reduced the colitis response by inhibiting CX3CL1/GNB5/AKT2/NF-κB/apoptosis pathway." (PMID 37446938, 2023). "Our research may shed light on the mechanism by which ALL inhibits the CX3CL1/GNB5/AKT2/NF-κB/apoptosis pathway and improves the intestinal barrier to reduce colitis response and act on the CX3CL1–CX3CR1 axis to achieve neuroprotection." (PMID 36831001, 2023).
Epileptic encephalopathy (2 papers, 2018 to 2020). A condition in which epileptiform abnormalities are believed to contribute to the progressive disturbance in cerebral function. "In contrast, the majority of patients carrying lof GNB5 alleles have early infantile developmental and epileptic encephalopathy as well as more significant ID." (PMID 30631341, 2018). "Following identification of her GNB5 variants and the reported clinical spectrum of IDDCA which includes early-onset sick sinus syndrome and epileptic encephalopathy among other cardinal manifestations, the patient was referred to cardiology and neurology." (PMID 30631341, 2018).
medulloblastoma (2 papers, 2014 to 2024). A malignant, invasive embryonal neoplasm arising from the cerebellum. "Some individual members of these pathways, including GNB3, GNB5, GABRA5, RCVRN and SAG were exclusively over-expressed in Group 3 medulloblastoma." (PMID 25412507, 2014).
Sinus bradycardia (2 papers, 2021 to 2023). Bradycardia related to a mean resting sinus rate of less than 50 beats per minute. "The asystole and sinus bradycardia found in the proband is consistent with GNB5-related disorder." (PMID 34573334, 2021).
Stroke (2 papers, 2019 to 2025). Sudden impairment of blood flow to a part of the brain due to occlusion or rupture of an artery to the brain. "Conversely, GNB5, which encodes a G protein β subunit involved in GPCR signaling, was downregulated following stroke." (PMID 41342963, 2025). "We showed that the expression of Dlg4, Gria1, Grin2a, Gng3, Gnb5, MapK8, and Bdnf (encoding PSD-95, GluA1, GluNMDA2A, G-protein subunit gamma 3, G-protein subunit beta 5, JNK, and BDNF, respectively) was strongly reduced 1 week after stroke." (PMID 31888302, 2019).
Anxiety (1 paper, 2021). Intense feelings of nervousness, tension, or panic often arise in response to interpersonal stresses. "For anxiety status, the identified GNB5 gene is the G protein subunit beta 5 (Gβ5) that encodes a heterotrimeric GTP binding protein." (PMID 34684344, 2021). "GWEIS identified multiple candidate loci, such as rs114086183 (p = 4.11 × 10−8, LRRTM4) for self-reported depression status and rs149760119 (p = 3.88 × 10−8, GNB5) for self-reported anxiety status." (PMID 34684344, 2021). "Therefore, we performed GWEIS and identified multiple candidate genes interacting with VD, which are implicated in the brain or neural regulation and pathology, such as LRRTM4 for depression status and GNB5 for anxiety status." (PMID 34684344, 2021). "For self-reported anxiety status, significant gene × VD PRS interaction was detected at the GNB5 gene (rs149760119, p = 3.88 × 10−8)." (PMID 34684344, 2021).
Ataxia (1 paper, 2022). Ataxia refers to impaired coordination of voluntary muscle movement. "Among the genes related to cerebellar volume in the four substructure GWASs we find genes related to ataxia (PEX7, MRPS27, PTK2), neurodevelopment (YPEL3, CASP6, TRIM11, GNB5) and microcephaly (PDCD6IP, USP28)." (PMID 35546225, 2022).
colorectal cancer (1 paper, 2021). A primary or metastatic malignant neoplasm that affects the colon or rectum. "Suppressing GNB5 increases cetuximab sensitivity in colorectal cancer cells and has been suggested as a combination therapy with cetuximab in cancer treatment." (PMID 34688260, 2021).
fluorosis (1 paper, 2023). "The top 10 drugs have been reported in previous studies, namely Celastrol, LDN-193189, XPNPEP1, GNB5, Importazole, LDHB, NUAK1, IFNG, IFNB1, and YWHAH, suggesting that these drugs may be effective candidate drugs for the treatment of fluorosis." (PMID 36835629, 2023).
Huntington disease (1 paper, 2022). Huntington disease (HD) is a rare neurodegenerative disorder of the central nervous system characterized by unwanted choreatic movements, behavioral and psychiatric disturbances and dementia. "One study showed that GNB5 is a hub gene in Huntington's disease (HD)." (PMID 35342758, 2022).
hyperlipidemia (1 paper, 2021). "Through the analysis of the hub genes in the network, it was found that targets such as PIK3R3, GNB5, and ESR1(ERα) have higher MCC values, suggesting that these genes were important targets for improving hyperlipidemia in PCE." (PMID 34925692, 2021). "Similarly, ESR1(ERα), MAOA, MGAM, PTK2, MMP1, GNB5, PIK3R3, and other targets had higher degree values, suggesting that these genes might be the core targets of PCE intervention in hyperlipidemia." (PMID 34925692, 2021).
ischaemia (1 paper, 2021). "[provided by RefSeq, Jul 2008] GNB5 is closely involved in the PI3K-Akt signalling and other pathways in placental ischaemia, and it also took part in placental insufficiency and IUGR, which is consistent with the previous research results." (PMID 34894939, 2021).